MMP9 (matrix metallopeptidase 9)
Diseases named in the same sentence as MMP9 in open-access papers (continued):
Sharing a sentence is not in itself a finding about the gene and the disease.
cancer (continued). "The MMP9, MMP12, MMP14, and MMP16 genes work synergistically to regulate processes such as tissue remodeling, wound healing, and cancer invasion." (PMID 39493455, 2024). "Plant-derived compounds, specifically polyphenols—the subject of this review—are suggested to play an important role in preventing cancer progression as MMP, especially MMP-2 and MMP-9, inhibitors." (PMID 39335164, 2024). "Transcription factors like NF-κB and STAT3, inflammatory enzymes such as COX-2 and MMP-9, and pro-inflammatory cytokines like IL-1, IL-6, IL-8, and TNF-α are crucial in inflammation-induced cancer." (PMID 39061221, 2024). "The findings suggest that MMP9 is involved in both the progression of CRC and the development of neuropathic pain, making it a key factor in understanding the impact of cancer treatment." (PMID 39664453, 2024). "The MMP9 gelatinase, a crucial member of the MMP family, contributes significantly to the pathogenesis and progression of numerous cancers." (PMID 38253629, 2024). "These non-coding RNAs affect the mRNA levels of Bcl2, TGFβ1, NFκB, VEGF, and matrix metalloproteinase 9 (MMP9), thereby activating corresponding signaling pathways that significantly increase cancer cell metastasis and induce EMT." (PMID 39578849, 2024). "Matrix metalloproteinase-9 (MMP-9) represents a major member of the MMP family, and its overexpression was confirmed in many human malignant tumors such as gastric, liver, lung, bone, skin, and breast." (PMID 39199694, 2024). "Consistent with our findings, a study reported the inhibition of cancer cell invasion via PI3K, NF-κB, and MMP-9 signaling pathways." (PMID 38811791, 2024). "The upregulation of RECK protein prevents the migration and invasion of cancer cells in hepatocellular carcinoma by downregulating the downstream protein STAT3 and matrix metalloproteinases like MMP2, MMP9, and MT1-MMP." (PMID 39456564, 2024). "The anti-cancer and anti-metastatic properties of genistein result largely from its ability to inhibit MMP-2 and MMP-9, as proven in many studies on various cancer cell lines." (PMID 39335164, 2024). "The interaction between MMP-9 and BCL-2 can promote cell survival and contribute to cancer progression." (PMID 38575697, 2024). "Regarding cancer biomarkers, Ki67, MMP2, and MMP9 protein levels were decreased by SAMD5 but increased by PLK1; PLK1 overexpression significantly alleviated the inhibitory effects of SAMD5 on these factors." (PMID 39524172, 2024). "The co-culture of ASCs with cancer cells leads to increased expression of MMPs, such as MMP-2, MMP-9, and MMP-14, in both ASCs and cancer cells." (PMID 39519109, 2024). "Other plant extracts have been reported to attenuate the migration and invasion of cancer cells by acting through MMP-2 and MMP-9 reduction." (PMID 38405665, 2024). "Remarkably, this is consistent with the mechanism that NE and MMP9 released during NETosis contribute to the destruction of the ECM, damaging the basement membrane and promoting cancer invasion and metastasis." (PMID 38662757, 2024). "Degradation of TSP-1 by NE and MMP9 within NETs 103 helps eliminate the inhibitory effect of TSP-1 on the reawakening of cancer cells, thus assisting in the reawakening of cancer cells." (PMID 38817858, 2024). "The urokinase plasminogen activator (uPA) and the MMPs, like MMP-2 and MMP-9, can destroy several ECM components and accelerate the spread and metastasis of cancer." (PMID 38481883, 2024). "The impact of PLE0 on the activity and expression levels of MMP-2 and MMP-9, two major MMPs that mediate ECM degradation, were investigated as the activity of MMP is critical in cancer metastasis." (PMID 38732748, 2024). "Among these, MMP-9, known for degrading the extracellular matrix (ECM), plays a crucial role in cancer cell migration." (PMID 38672844, 2024).
cancer (continued). "The small size of these molecules enables them to penetrate tissues and reach intracellular targets efficiently and via inhibiting MMP-2 and MMP-9, these small molecules prevent the breakdown of the ECM, thereby limiting cancer cell invasion and metastasis." (PMID 39858430, 2024). "Similar to MMP-2, MMP-9 (also known as gelatinase B) degrades gelatin and type IV collagen, and exosomal thrombospondin-1 (THBS1) binds to FAK and MMP-9 to prevent ECM stiffness-dependent cancer invasion." (PMID 38544822, 2024). "Compared with normal tissues, the expression levels of MMP9 and SCGN generally changed in pan-cancer." (PMID 38375034, 2024). "Schisandrin A (SchA), a good anti-cancer drug, significantly down-regulated EGFR, PIK3R1, and MMP9 but up-regulated cleaved-caspase 3, thus inhibiting the migration and promoting the apoptosis of MDA-MB-231 cells." (PMID 39190284, 2024). "Cancer cells rely on the overexpression of MMP-2 and MMP-9 to travel from the source cells to nearby tissues." (PMID 38672151, 2024). "This study summarized how natural products from natural fruits and vegetables as well as marine organisms have been shown to have positive impacts on cancer by downregulating the actions and/or levels of MMP-2 and MMP-9." (PMID 38672151, 2024). "Expression of MMP2 and MMP9 is regulated by fatty acid-binding protein 5 (FABP5), a cancer metastasis promoting protein." (PMID 38215076, 2024). "Metastatic CRC cells release proteolytic enzymes like matrix metalloproteinase 2 (MMP-2) and matrix metalloproteinase 9 (MMP-9) to digest the extracellular matrix (ECM), facilitating irregular cancer cords to penetrate adjacent tissues." (PMID 38468952, 2024). "In a cisplatin-resistant OSCC cell line, non-toxic concentrations (50 μM) of resveratrol depleted the migration and invasive capabilities of cancer cells by reducing the mRNA and protein expression of MMP-2 and MMP-9." (PMID 39335164, 2024). "Selenite impedes the invasive capabilities of cancer cells by curtailing the activity of MMP-2 and MMP-9, as well as uPA." (PMID 39839762, 2024). "It was shown that this system presented stratification between cancer and stromal cells, accompanied by the expression of several soluble factors found in human pancreatic cancer such as TGF-β, FGF-2, IL-1β, and MMP-9." (PMID 38254117, 2024). "Nuclear TSPAN8 interacts with the transcription factor STAT3 to activate the transcription of cancer-promoting genes including MYC, BCL-2 and MMP9, which in turn promotes tumorigenesis." (PMID 38275818, 2024). "MMPs, especially MMP-2 and MMP-9, play essential roles in cancer metastasis by degrading key components of the ECM, thereby creating pathways for cancer cells to invade and metastasize." (PMID 39062544, 2024). "To validate our findings, we recruited a cohort of 21 cancer patients for histological confirmation, revealing significant mRNA upregulation of STAT3, IL6, MMP9, MMP3, TGFB1, VEGF and HIF1A, coupled with downregulation of LHPP and PCK1, PTEN and BLC2." (PMID 39468431, 2024). "The prognostic value of high expression levels of MMP9, MMP12, MMP14, and MMP16 in various cancers, as indicated in this study, has also been reported in prior research." (PMID 39493455, 2024). "MMP-9 and MPO are components of NETs present on externalized nuclear DNA that promote endothelial cell and cancer cell proliferation." (PMID 38730718, 2024). "STAT5A signaling, CSPG4, MMP-1, MMP-3, MMP-8, MMP-9, and LUM are all involved in cancer cell migration, invasion, and metastasis, while PKM supports the growth and survival of cancer cells by favoring aerobic glycolysis." (PMID 39201614, 2024). "In certain cancer cells, HMGA1 can activate the PI3K/Akt signaling pathway and upregulate the expression of matrix metalloproteinase 9 (MMP-9)." (PMID 39507236, 2024). "The interaction between matrix metalloproteinases (such as MMP-2 and MMP-9) and VEGF is a key focus in cancer research, given their combined impact on cancer progression and metastasis." (PMID 38374934, 2024).
cancer (continued). "The PI3K/AKT signaling pathway was reported to be involved in the epithelial–mesenchymal transition (EMT) and matrix metalloproteinase 9 (MMP9) activity, promoting the invasiveness and metastasis of cancer cells." (PMID 38473784, 2024). "Subsequent studies corroborated that eHsp90 interacts with cancer cell secreted MMPs- particularly the inactive zymogen forms of MMP-2 and MMP-9." (PMID 39594828, 2024). "MMP-9 and MMP-2 are the principal proteolytic enzymes that promote cancer cell invasion by decomposing the basement membrane and then triggering cancer metastasis." (PMID 38904007, 2024). "LCN2 contributes to CRC progression by forming a complex with MMP9, an enzyme involved in degrading the extracellular matrix (ECM), thus enhancing cancer cell invasion and metastasis." (PMID 39839775, 2024). "MMP2, MMP9, and MMP14 have been shown to enhance cancer progression due to their ability to degrade basement membrane components." (PMID 39066315, 2024). "After infection, we quantified changes in the cellular cancer phenotypes, the gene expression levels of some cancer markers, including Ki-67, BCL-2, VIM, MMP9, and VEGF, and proinflammatory cytokines." (PMID 39427065, 2024). "KB: human epithelial carcinoma, Ct: cycle threshold, MMP-9: matrix metallopeptidase 9, mRNA: messenger ribonucleic acid." (PMID 38481883, 2024). "Recent studies indicated that Snail can mediate the upregulation of several gene expressions of MMPs in cancers such as MMP-2, MMP-9, and MMP-14, and these proteases were reported to be promoters and mediators of EMT processes in cancers." (PMID 36766694, 2023). "Although MMP-9 regulates metastatic progression in cancer invasion, the KD of CRP2 hardly affects the expression of MMP-9 in CAFs." (PMID 37164693, 2023). "Similar types of MMPs were found to be increased in both cancers, namely, MMP-1, MMP-2, MMP-9, and MMP-11." (PMID 36982551, 2023). "Relative cancer invasion markers matrix metalloproteinase 2 (MMP-2), E-cadherin, MMP-9, epithelial-cell adhesion molecule (EpCAM), and N-cadherin in the LOC model were detected via immunohistochemical (IHC) staining." (PMID 37771785, 2023). "In endometrial carcinoma, CAFs promote cancer progression via the SDF-1α/CXCR4 axis, through PI3K/AKT and MAPK/ERK signaling in a paracrine-dependent manner, and increase MMP-2 and MMP-9 secretion in an autocrine-dependent manner." (PMID 37046676, 2023). "In NSCLC, overexpression of CTHRC1 contributes to cancer invasion and metastasis in a MMP7- and MMP9-dependent manner." (PMID 37766868, 2023). "In this regard, matrix metalloproteinases (MMPs), including MMP9, are key enzymes for ECM degradation, while intratumoral MMP9 expression is positively correlated with the aggressiveness of many cancers." (PMID 36675289, 2023). "In NSCLC, cancer recurrence and metastasis are closely related to CSC, and these cells induced MMP-9 secretion." (PMID 37766868, 2023). "MMP-2 and MMP-9 are the major enzymes involved in the degradation of extracellular matrix (ECM) and plays crucial role in the metastatic dissemination of cancer cells." (PMID 37370134, 2023). "In many types of cancer, the downregulation of RECK gene expression related to the expression and the activity of MMPs, such as MMP-2 and MMP-9, has been demonstrated." (PMID 38139236, 2023). "It was reported that phytochemicals have significant anti‐metastatic and anti‐angiogenesis effects by inhibiting MMP‐9 and MMP‐2 and suppressing VEGFR‐2 expression, thereby inhibiting the growth and invasiveness and adhesion of cancer cells." (PMID 37132286, 2023). "Isoliquiritigenin (25–50 μM) treatment inhibited signaling molecules such as NF‐κB, P13K/Akt, and p38, decreasing MMP‐2, MMP‐9, VEGF, and HIF‐1α expressions leading to reduce the motility of MDA‐MB‐231 cancer cells." (PMID 37132286, 2023).
cancer (continued). "This LncRNA is highly expressed in various cancer types and exerts its tumorigenic effects by blocking the PI3K/Akt pathway and increasing matrix metalloproteinase-9 (MMP-9)." (PMID 36770654, 2023). "Matrix metalloproteinases (MMPs) are closely related to angiogenesis, invasion, metastasis, and the avoidance of immune surveillance in the course of cancer, among which MMP1 and MMP9 are universally upregulated in almost all cancers." (PMID 37202657, 2023). "Overall, the effect of dandelion, or its combination with ATRA, on the expressions of MMP-2 and MMP-9 in MDA-MB231 and MCF-7 cells should be considered a novel finding that can be used in cancer treatment strategies by conducting further research." (PMID 37700002, 2023). "The M2-like TAMs then facilitated cancer cell escape by secreting high levels of IL-10, VEGF, PGE2, and MMP-9." (PMID 37210553, 2023). "MMP-9 also helps facilitate the process of EMT by cleaving and inactivating the cell junction protein E-cadherin, thus helping the cancer cell escape the primary tumor site." (PMID 38068928, 2023). "Firstly, two analysis databases including UALCAN and GEPIA were used, and the results revealed that as for MMP9 and IRF7 genes, they gain of expression in most of human cancers." (PMID 37438709, 2023). "Either siRNA silencing or CRISPR-Cas9-based knockout of AHR prevented expression of CYP1A1, but amplified the expression of MMP9, CXCL12 and CXCR4 that contribute to the tumorigenesis and metastasis of the cancer cells." (PMID 37151890, 2023). "Taken together, LCN2, LOXL2, and MMP9 are highly expressed in ESCC, and are emerging as promising therapeutic targets in many types of cancer." (PMID 37753805, 2023). "We also observed differential expression of cancer-metastasis-inducing genes, such as ZEB1, MMP9, CLDN3, TWIST1 and N-cadherin, between LVI(+) and LVI(−) samples in some patients, indicating a correlation of VCAN with EMT genes in LVI(+) samples." (PMID 37108649, 2023). "Cancer cells degrade the extracellular matrix barrier through secreting MMP2 and MMP9, and subsequently bind to adhesion receptors on the basement membrane, promoting cell mobility." (PMID 37940982, 2023). "Several studies have shown that the anti-cancer properties of numerous SFB species are strongly correlated with their capacity to inhibit MMPs, notably the expression of MMP-2 and MMP-9." (PMID 37175435, 2023). "MMP-14 has a central role among the MMPs and acts in cancer metastasis by degrading the ECM, increasing the secretion of pro-MMP2, pro-MMP9 and pro-MMP13, while cleaving membrane-anchored growth factors and cytokines." (PMID 36656313, 2023). "In the study, piperine was shown to downregulate MMP-9 expression by inhibiting PKCα/ERK1/2 and NF-κB/AP-1 pathways in a PMA (phorbol-12-myristate-13-acetate)-induced cancer model in vitro." (PMID 37298797, 2023). "The major gene targets of four core herbs, MMP9, BCL2, STAT1, and STAT3, each as a subset of pathways in cancer, were confirmed to be involved in the MAPK pathway, the mTOR pathway, and cytokine–cytokine receptor interaction." (PMID 37631075, 2023). "MMPs secreted by SCs, especially MMP2 and MMP9, enhance the degradation of ECM and provide loose channels for the movement of cancer cells." (PMID 36900158, 2023). "Ongoing studies on this group of enzymes suggest that cancer cells can secrete and/or induce osteoclasts to release enzymes, including MMP-2 and MMP-9, into the bone microenvironment." (PMID 38138968, 2023). "The 10-biomarker signature in this category additionally incorporating FABP5, C1RL, MMP9, ECM1, S100A7 and CF1, discriminated early-stage cancers from controls with an AUC of 0.92 (0.86–0.97)." (PMID 36807337, 2023). "Due to the characteristics of participating in the recurrence and metastasis of a variety of cancers, Fn-1, S100A8, S100A9, and MMP9 were regarded as the main components of the formation of the pre-metastatic microenvironment." (PMID 37330523, 2023).
cancer (continued). "MMPs (MMP-2, MMP-9, MMP-14) are able to damage the capillary layer and at the same time promote the exosmosis of cancer cells." (PMID 37895400, 2023). "Most MMPs have consistently increased gene expression across cancers, and MMP1, MMP9, MMP10, MMP11, and MMP13 are almost universally upregulated across a wide variety types of cancers." (PMID 36903626, 2023). "Cancer aggressiveness-related proteins, such as N-cadherin, Vimentin, Twist, MMP-2, MMP-9, and MMP-13, and the glycolytic enzymes PKM2 and GLUT1 were upregulated in ERL-R cells." (PMID 36611972, 2023). "MMP-2 and MMP-9 can degrade ECM proteins, thereby overcoming the physical barriers preventing cancer cell invasion into nearby tissues or metastasis to distant sites." (PMID 37760801, 2023). "In the process of cancer angiogenesis, curcumin inhibits the growth factor VEGF and ensures stability of the extracellular matrix, which downregulates MMP-2 and MMP-9 and upregulates metalloproteinase-1." (PMID 37513855, 2023). "These included multiple ligands with previously supported roles in cancer cell invasion, including TGF-β1, IL-6, CXCL12, and MMP9, underscoring the robustness of our approach." (PMID 36881486, 2023). "MMP-9 has an important role in ECM remodeling, metastasis, angiogenesis, apoptosis, and cancer progression." (PMID 36938194, 2023). "One mechanism is the production of MMP-9 by TAMs, which contributes to tumor angiogenesis, extracellular matrix (ECM) remodeling, and cancer cell invasion through the ECM, ultimately promoting cancer cell metastasis." (PMID 37663266, 2023). "Thousands of mRNAs are ELAVL1 targets, including factors fostering diverse cancer traits such as proliferation (cyclins A2, B1, D1, and E1), angiogenesis (HIF1a, PTGS2, and VEGFA), survival (BCL2 and MCL1), and invasion (MMP9 and SNAI1)." (PMID 37298909, 2023). "The release of IL-1β, IL-8, TNF-α, TGF-β, MMP-2, and MMP-9 by macrophages is involved in epithelial-mesenchymal transition (EMT), which promotes cancer cell invasion and metastasis." (PMID 38137361, 2023). "Recently, Augoff's group also exhibited that MLN4924 possessed a significantly inhibitory efficacy on the tumor necrosis factor-alpha (TNF-α)-induced activity of MMP9 in ESCC cells, which further inhibited MMP9-dependent cancer cell migration." (PMID 37771770, 2023). "First and foremost it has been established that the substantial functioning of ADAM8 lies in the extracellular liberation of MMP-9 and LCN2, which are two key facilitators of cancer advancement in PDAC." (PMID 36910158, 2023). "MMP‐9, a component of the tertiary granules, is shown to be secreted by neutrophils in the TME of multiple cancer types." (PMID 38062888, 2023). "In accordance with the literature, we found that the MMP-9 signal was stronger in the 3D CRC μTs than in the 3D Stroma μTs, and it was particularly localized in both the fibroblast and cancer cell protrusions of the plasma membrane." (PMID 36982752, 2023). "But our study shows that WSP is dose-dependent, and the dose in mice can reach 60μg/g, and the expression of proteins related to cancer metastasis, such as MMP2 and MMP9, is observed to decrease." (PMID 36568183, 2022). "While PRSS8 has clearly been shown to promote apoptosis in multiple cancer contexts through regulation of several relevant proteins (PTEN, Bax, and MMP9), the role of HMOX1 in regulating apoptosis appears to vary across tissues." (PMID 36457077, 2022). "An important factor promoting the migration of cancer cells is TNF-α, a pro-inflammatory cytokine that, among its many biological functions, also plays a major role in mediating the expression of MMP9, one of the key regulators of cancer cell migration." (PMID 36555705, 2022). "MEL also specifically inhibits matrix metalloproteinase-9 (MMP-9) production, which is crucial for cancer cell motility, by downregulating activator protein-1 (AP-1) and NF-B expression." (PMID 35708464, 2022).